DGCR8 (DGCR8 microprocessor complex subunit)
Description:
Component of the microprocessor complex that acts as a RNA- and heme-binding protein that is involved in the initial step of microRNA (miRNA) biogenesis. Component of the microprocessor complex that is required to process primary miRNA transcripts (pri-miRNAs) to release precursor miRNA (pre-miRNA) in the nucleus. Within the microprocessor complex, DGCR8 function as a molecular anchor necessary for the recognition of pri-miRNA at dsRNA-ssRNA junction and directs DROSHA to cleave 11 bp away form the junction to release hairpin-shaped pre-miRNAs that are subsequently cut by the cytoplasmic DICER to generate mature miRNAs. The heme-bound DGCR8 dimer binds pri-miRNAs as a cooperative trimer (of dimers) and is active in triggering pri-miRNA cleavage, whereas the heme-free DGCR8 monomer binds pri-miRNAs as a dimer and is much less active. Both double-stranded and single-stranded regions of a pri-miRNA are required for its binding. Specifically recognizes and binds N6-methyladenosine (m6A)-containing pri-miRNAs, a modification required for pri-miRNAs processing. Involved in the silencing of embryonic stem cell self-renewal (By similarity). Also plays a role in DNA repair by promoting the recruitment of RNF168 to RNF8 and MDC1 at DNA double-strand breaks and subsequently the clearance of DNA breaks.
Synonyms: C22orf12; DGCRK6; Gy1; pasha
Tractability: PROTAC: UniProt records ubiquitination sites on it; ubiquitination databases record sites on it; its protein half-life has been measured.
Gene: Protein-coding gene on chromosome 22 (20,080,035 to 20,111,877, forward strand). Ensembl gene ENSG00000128191.
Subcellular location: Nucleus; Nucleus, nucleolus
Subcellular location (Human Protein Atlas): Nuclear bodies; Nucleoplasm
Pathways (Reactome):
Gene expression (Transcription): MicroRNA (miRNA) biogenesis
Gene Ontology:
Molecular function: double-stranded RNA binding; heme binding; identical protein binding; primary miRNA binding; protein binding; protein homodimerization activity; protein-macromolecule adaptor activity; protein-RNA adaptor activity; RNA binding
Biological process: DNA damage response; positive regulation of pre-miRNA processing; primary miRNA processing
Cellular component: cytoplasm; microprocessor complex; nuclear body; nucleoplasm; nucleus; site of double-strand break; glutamatergic synapse; nucleolus; organelle; postsynaptic density
Genetic constraint (gnomAD): Loss-of-function variants: 12 observed, 71.97 expected, observed/expected ratio (o/e) 0.17, 90% interval 0.11 to 0.27. The upper end of that interval is the gene's LOEUF score, 0.27, which puts it in group 1 of 6, group 1 being the genes least tolerant of losing a copy. Missense variants: 671 observed, 1,022.7 expected, observed/expected ratio (o/e) 0.66, 90% interval 0.62 to 0.7. Synonymous variants: 380 observed, 404.5 expected, observed/expected ratio (o/e) 0.94, 90% interval 0.86 to 1.02.
Homologues: Orthologues: chimpanzee DGCR8 (100% identical), macaque DGCR8 (99% identical), dog DGCR8 (96% identical), guinea pig DGCR8 (96% identical), mouse Dgcr8 (95% identical), rabbit DGCR8 (95% identical), rat Dgcr8 (95% identical), pig DGCR8 (94% identical), tropical clawed frog dgcr8 (77% identical), zebrafish dgcr8 (71% identical), Drosophila melanogaster pasha (30% identical), Caenorhabditis elegans pash-1 (22% identical).
Diseases named in the same sentence as DGCR8 in open-access papers:
DGCR8 is named in the same sentence as 127 diseases in open-access papers, as found by Europe PMC text mining. Sharing a sentence is not in itself a finding about the gene and the disease. The quoted sentences say what the papers report.
schizophrenia (35 papers, 2007 to 2025). A major psychotic disorder characterized by abnormalities in the perception or expression of reality. "We had previously reported that blocking NMDAR in monkeys and deleting a schizophrenia risk gene (Dgcr8) in mice, both reduced the frequency of synchronous, 0-lag spiking between prefrontal neurons." (PMID 38319151, 2024). "Several genes likely implicated in the pathogenesis of schizophrenia have been identified as targets for miRNA altered by DGCR8 haploinsufficiency, including DISC1, RELN and SYN1." (PMID 38540380, 2024). "We, therefore, chose 5 SNPs (rs1640299, rs2286928, rs417309, rs720012, and rs3757) from 3′ UTR of DGCR8 to conduct an association study in 1034 schizophrenia patients and 1,034 healthy controls in the Han Chinese population." (PMID 35492695, 2022). "We found that the G allele and GG genotype of rs3757 in DGCR8 conferred a higher risk of schizophrenia, which likely resulted from higher expression of DGCR8 according to our test of dual-luciferase reporter system." (PMID 35492695, 2022). "Further refined studies, extended to DGCR8-associated microRNAs and related pathways to confirm the underlying molecular mechanisms involved in the development of schizophrenia, are clearly warranted." (PMID 35492695, 2022). "Previous studies have found that the 22q11.2 locus, containing DGCR8, confers a risk of schizophrenia." (PMID 35492695, 2022). "In summary, the present study showed for the first time that rs3757 at 3′ UTR of DGCR8 was associated with schizophrenia via upregulating the expression of DGCR8 in the Chinese Han population." (PMID 35492695, 2022). "Collectively, these experiments were broadly shed light on the role of Dgcr8 in the regulation of miRNA-associated pathway contributing to the pathophysiology of schizophrenia." (PMID 35492695, 2022). "A mutation in Dgcr8, a candidate gene for 22q11.2 deletion-associated schizophrenia, leads to decreased adult hippocampal neurogenesis in mice." (PMID 33673334, 2021). "The mouse model for haploinsufficiency of the Dgcr8 gene shows abnormal miRNA biogenesis caused by decreased Dgcr8 gene expression, schizophrenia-like deficits, and decreased neurogenesis in the adult hippocampus." (PMID 33581109, 2021). "The location of DiGeorge critical region gene 8 (DGCR8), part of the enzyme complex that cleaves the pri-miRNA gene product into pre-miRNA, within the chromosome 22q11.2 schizophrenia-susceptibility region has given considerable weight to this idea." (PMID 29657307, 2018). "Under investigation is the potential importance of Dgcr8 in Di George syndrome, a multifaceted disorder where 30 genes including Dgcr8 are deleted, and has been associated with schizophrenia." (PMID 26635721, 2015). "Deregulations of DGCR8 expression associating with the aberrant expressions of miRNAs have also been detected in many diseases such as schizophrenia and different kinds of cancers." (PMID 26202964, 2015). "In keeping with this, the hippocampal expression of IGF2 was found to rescue adult neurogenesis and improve spatial working memory deficits in the Dgcr8 (DiGeorge syndrome chromosomal region 8) deficient mouse model of schizophrenia (Ouchiet al, 2013)." (PMID 25100745, 2014). "A key protein implicated in this dysregulation is Dgcr8, which is located on chromosome 22, within a section (22q11.2) known to be deleted in some patients with schizophrenia." (PMID 23805071, 2013). "In human populations, microdeletions that include the DGCR8 gene (PASHA) cause DiGeorge syndrome—a multispectrum disorder associated with a high risk of schizophrenia." (PMID 23847651, 2013). "The abnormality of Dgcr8± mice and strong association between 22q11.2 microdeletion and schizophrenia prompted us to speculate that DGCR8 expression levels could affect susceptibility to schizophrenia." (PMID 35492695, 2022).
schizophrenia (continued). "Since the overexpression of Dgcr8 associated with human schizophrenia, we asked whether enhancing the expression of Dgcr8 would affect mice behaviors and cognition." (PMID 35492695, 2022). "Concordant with the reporter gene assay showing that the luciferase activity of DGG was higher than that of DGA, it can be presumed that the polymorphism of rs3757 confers susceptibility to schizophrenia by regulating DGCR8 expression through changing the stability of DGCR8 transcript." (PMID 35492695, 2022). "Our association study identified rs3757 in DGCR8 gene as a vulnerable factor to schizophrenia." (PMID 35492695, 2022). "Widespread miRNA dysregulation attributable to DGCR8 hemizygosity may serve as part of the “threshold lowering” mechanism of the 22q11.2 deletion for schizophrenia risk." (PMID 35495153, 2022). "It is thought that this variation might be associated with the risk of schizophrenia with 22q11 deletion syndrome caused by disruption of the DGCR8 gene." (PMID 33581109, 2021). "The 22q11.2 microdeletion, as a risk factor of schizophrenia, may act through haploinsufficiency of DGCR8 and depletion of downstream miRNAs." (PMID 34955759, 2021). "We identified miRNAs overlapped by the 22q11.2 microdeletion and for the first time investigated their predicted target genes, and those implicated by DGCR8, to identify targets that may be involved in the risk for schizophrenia." (PMID 25484875, 2014). "Several schizophrenia-associated genes were down-regulated in the hippocampus of Dgcr8+/- mice, including the insulin-like growth factor 2 (IGF2), which was recently found to play a crucial role in hippocampal functions such as memory consolidation and fear extinction." (PMID 24367288, 2013). "As a final note, DiGeorge critical region 8 (DGCR8), involved in miRNA biogenesis as a component of the microprocessor, is located in a genomic region of chromosome 22q11 where microdeletions have been associated with a 30-fold increased risk of schizophrenia." (PMID 17326821, 2007). "Possibly, DGCR8 polymorphisms that alter expression or function through haploinsufficiency or other genetic variants might also contribute to the etiopathology of schizophrenia by impacting miRNA biogenesis and regulation of gene expression." (PMID 17326821, 2007). "DiGeorge syndrome is caused by the chromosomal deletion 22q11.2, where the DGCR8 gene is located, and patients often show cognitive and behavioral impairment; in fact, this deletion is one of the well-established risk factors for the development of schizophrenia." (PMID 33581109, 2021). "Still, in light of our findings, Dgcr8+/- mice may be useful to probe whether loss of compensatory mechanisms in regulating neuronal miRNA expression during development may contribute to any of the emergent phenotypes of schizophrenia and autism." (PMID 21466685, 2011). "Our investigation is, therefore, the first to report the correlation between DGCR8 and schizophrenia based on genetic factors in relative large Chinese population (1,034 schizophrenia patients versus 1,034 health control)." (PMID 35492695, 2022). "In the present study, we try to identify the role of DGCR8 in schizophrenia from human samples and animal models." (PMID 35492695, 2022). "In the case of schizophrenia, the role of DiGeorge syndrome critical region gene 8 (DGCR8) 22q11.2 deletion was commonly cited as a well-studied example of miRNA abnormality that is linked to a higher likelihood of developing the disorder." (PMID 36613876, 2022). "While the link of schizophrenia with 22q11.2 deletions as well as DGCR8 depletion has been well-established in the animal study, there are few functional studies of microduplications of DGCR8/22q11.2 in schizophrenia." (PMID 35492695, 2022). "Another work analyzed three SNPs in DGCR8 (rs2531721, rs374225, and rs2073778) among schizophrenia patients of Ashkenazi Jewish origin and the results still failed to reach statistical significance." (PMID 35492695, 2022).
schizophrenia (continued). "It was shown that IGF-2 treatment restores some cognitive impairments in mouse models of schizophrenia (Dgcr8+/−) and AD (Tg2576)." (PMID 33673334, 2021). "Genetic association studies have reported associations between SNPs in DGCR8 (rs3757, rs8139591, rs9606248) and the pre-miRNA processing gene DICER1 (rs3742330, rs11621737) and the incidence of schizophrenia in Han Chinese patients." (PMID 29657307, 2018). "The abnormal expression of DGCR8 accompanying with disordered miRNA biogenesis has been discovered in diverse diseases, such as cancers and schizophrenia." (PMID 26202964, 2015). "We also observed a statistically significant overlap between target genes of miRNAs predicted to be dysregulated by hemizygous deletion of DGCR8 and the schizophrenia network." (PMID 25484875, 2014). "We found that the predicted gene targets of the 22q11.2 deletion miRNAs, and targets of the genome-wide miRNAs predicted to be dysregulated by DGCR8 hemizygosity, were significantly represented in this schizophrenia network." (PMID 25484875, 2014). "Alterations in thalamic-cortical functional connectivity in 22qDel mice have been related to changes in the auditory thalamus mediated by microRNA processes downstream of the 22q11.2 gene Dgcr8, which have been corroborated in human post-mortem tissue from individuals with schizophrenia." (PMID 38431758, 2024). "In another study, DGCR8 heterozygosity in mice led to a decreased rate of neurogenesis in the adult hippocampus and to altered hippocampus-dependent learning, as well as to the downregulation of some schizophrenia-related genes." (PMID 38540380, 2024). "Nevertheless, more immediate evidence from postmortem cerebral samples of individuals with schizophrenia showed DGCR8 overexpressed in several region, including hippocampus superior temporal cortex and dorsolateral prefrontal cortex, which strongly supported our results." (PMID 35492695, 2022). "Indeed, evidence is showing that aberrant expression of DGCR8 was demonstrated in schizophrenia patients although the results are incongruence." (PMID 35492695, 2022). "Together, these results demonstrate that DGCR8 may play a role in the etiology of schizophrenia through regulating neural development." (PMID 35492695, 2022). "This indicated that the DRE RNA element of pri-miR-9-2 may be unique for potentiating DGCR8-dependent processing and that it might be required for pursuing the link to schizophrenia in the future." (PMID 33581109, 2021). "Exogenous IGF-2 could reverse the spatial working memory deficits in Dgcr8(+/-) mice, a neurodevelopmental defect model for schizophrenia, by rescuing the proliferation of adult neural stem cells in the hippocampus." (PMID 32191705, 2020). "Consistent with a miRNA hypothesis for schizophrenia, restricting to genes predicted to be affected by DGCR8 haploinsufficiency tended to increase estimated effect sizes, despite the decrease in number of variants per subject." (PMID 26384369, 2015). "In the current study, we hypothesized that the effect of a 22q11.2 deletion on phenotypic expression of schizophrenia could involve not only the hemizygosity of DGCR8 but also reduced dosage of all of the miRNAs within the 22q11.2 deletion region." (PMID 25484875, 2014). "Consistent with our hypothesis, we found evidence that the effect of a 22q11.2 deletion on phenotypic expression of schizophrenia could involve not only the hemizygosity of DGCR8 but also reduced dosage of all of the miRNAs within the 22q11.2 deletion region." (PMID 25484875, 2014). "First, the gene encoding the DiGeorge syndrome critical region gene 8 protein (DGCR8), one of the components of the nuclear miRNA processing complex, is located in a chromosomal location (22q11.2) associated with high risk for schizophrenia." (PMID 23637704, 2013). "However, the role of DGCR8 in schizophrenia and the early stage of neural development has remained unknown." (PMID 35492695, 2022).
schizophrenia (continued). "Thus, we hypothesized that DGCR8 may be partially responsible for schizophrenia and abnormal expression of DGCR8 may result in developmental deficits in the neural system and abnormal behavioral phenotype in adulthood." (PMID 35492695, 2022). "In addition, IGF-2 protein was downregulated in the hippocampus of mice lacking DiGeorge chromosome syndrome region 8 (Dgcr8), a candidate gene for 22q11.2 deletion-associated schizophrenia." (PMID 32191705, 2020). "However, despite a number of systematic investigations of genes in the 22q11.2DS region and the ever increasing number of GWAS data sets, no genetic study to date has identified common variation in DGCR8 or MIR185 as a risk factor for schizophrenia." (PMID 24367288, 2013). "Specific attention is given to the impact of SNPs in DICER, DROSHA, and DGCR8, as well as the potential for changes in DRD2 gene expression driven by miR-9 and miR-326, heightening the likelihood of Schizophrenia development." (PMID 38343691, 2024). "DiGeorge Syndrome Critical Region Gene 8 (DGCR8) is a key component of the microprocessor complex governing the maturation of most microRNAs, some of which participate in schizophrenia and neural development." (PMID 35492695, 2022). "In Brodmann area (BA) 9 of the DLPFC, DGCR8, DROSHA, and DICER1 have all be reported to be increased in schizophrenia with other miRNA processing proteins, such as XPO5, which is reported as unchanged." (PMID 29657307, 2018). "Interestingly, restoration of IGF2 expression in the hippocampus rescued the observed spatial working memory deficits in Dgcr8+/- mice, suggesting that IGF2 contributes – at least in part – to the learning and spatial working memory deficits that are associated with 22q11.2DS-related schizophrenia." (PMID 24367288, 2013). "As an example, HTR2C, one of seven genes dramatically decreased in Dgcr8± mutant mice hippocampus and previously shown to be decreased in prefrontal cortex in schizophrenia, though present in our network, was not a predicted DGCR8 target using our methods." (PMID 25484875, 2014). "This suggests that these molecules (and possibly many others regulated by the Dgcr8–miRNA-dependent mechanism) serve as a common mechanistic node between schizophrenia cases arising from the 22q11.2 microdeletion and idiopathic cases of the disease (without CNVs)." (PMID 34955759, 2021).